CRP (C-reactive protein)
Diseases named in the same sentence as CRP in open-access papers (continued):
Sharing a sentence is not in itself a finding about the gene and the disease.
hypopituitarism (4 papers, 2022 to 2023). A condition of diminution or cessation of secretion of one or more hormones from the anterior pituitary gland. "Previous studies have established that patients with hypopituitarism exhibit increased CRP levels." (PMID 38024646, 2023). "In a cross-sectional study that enrolled 53 women with hypopituitarism and 111 healthy control women, interleukin-6 (IL-6) and CRP concentration were significantly higher in women with hypopituitarism than in healthy controls and were attributed to GH and estrogen deficiency." (PMID 36742387, 2023). "Patients with hypopituitarism have been observed to exhibit elevated CRP levels." (PMID 38024646, 2023).
iron disorder (4 papers, 2009 to 2024). "Compared with patients with no iron disorder, those with non-inflammatory functional ID had higher BMI and CRP values and lower serum albumin levels." (PMID 24586229, 2014).
Left ventricular diastolic dysfunction (4 papers, 2020 to 2023). Abnormal function of the left ventricule during left ventricular relaxation and filling. "Studies had confirmed the relationship between CRP, TNF, and CSAP, which indicated TNF-α had an association with left ventricular diastolic dysfunction while CRP was related to the reoccurrence of CSAP." (PMID 33110434, 2020). "Regardless of sex, hypertensive patients with the second stage of the left ventricular diastolic dysfunction have significantly higher (compared to the first stage) systemic blood concentrations of C-reactive protein, tumor necrosis factor alpha, and interleukin-6." (PMID 35997392, 2022). "Moreover, there were significant differences between the two groups in the following aspects, such as β‐blocker use, LAD, EF, Left ventricular diastolic dysfunction, AR, MR, TR, LVSD, Pah, LYMPH, NLR, TG, hs-CRP and SChE." (PMID 37941017, 2023).
lumbar disc herniation (4 papers, 2020 to 2025). "The inflammatory marker CRP and cytokines can be increased in the peripheral blood of patients with lumbar disc herniation and thus have important significance for clinical diagnosis and disease surveillance." (PMID 33441130, 2021). "It is noteworthy that CRP has not yet been established as a marker indicative of lumbar disc herniation." (PMID 37803313, 2023).
macrosomia (4 papers, 2015 to 2022). "However, after adjusting for prepregnancy BMI, gestational weight gain, parity, history of macrosomia delivery, history of GDM/DM, HbA1c, and CRP, maternal TC level remained an independent risk factors of macrosomia in multivariate logistic regression analysis." (PMID 35513792, 2022). "Probiotics also reduced the level of inflammatory markers (high-sensitivity C-reactive protein, interleukin-6, tumor necrosis factor-α, and malondialdehyde), incidence of macrosomia, and newborn hospitalization." (PMID 34578921, 2021). "An intervention of low GI advice had no impact on levels of CRP in women with a high risk of GDM nor on IL-6 and TNF-α in women at high risk for macrosomia in the second half pregnancy." (PMID 33806342, 2021).
malignant pleural mesothelioma (4 papers, 2017 to 2023). A malignant neoplasm that arises from mesothelial cells in the pleura and shows a diffuse growth pattern. "Yoshida N, Baba H. The C-reactive protein/albumin ratio may predict the long-term outcome in patients with malignant pleural mesothelioma." (PMID 33331459, 2021).
Mastoiditis (4 papers, 2018 to 2025). "Children younger than 2 years were treated at higher dosage for mastoiditis, probably because they were more frequently feverish and they had higher levels of CRP and WBC." (PMID 29914542, 2018). "This study highlights the importance of recognizing subtle neurological abnormalities, prior antibiotic treatment, elevated CRP levels, and prolonged fever as key predictors of CSVT in children with mastoiditis." (PMID 41039147, 2025).
Miscarriage (4 papers, 2020 to 2024). A pregnancy that ends at a stage in which the fetus is incapable of surviving on its own, defined as the spontaneous loss of a fetus before the 22th week of pregnancy. "We did not observe a role for hs-CRP levels in the association between miscarriage and CVH scores." (PMID 37113178, 2023).
myelodysplastic syndrome (4 papers, 2019 to 2024). A clonal hematopoietic disorder characterized by dysplasia and ineffective hematopoiesis in one or more of the hematopoietic cell lines. "Elevated CRP has been reported to have an independent prognostic impact in myelodysplastic syndrome subjects, whereas elevated values can indicate clonal hematopoiesis and non-hematological comorbidities in cases with low-risk myelodysplastic syndromes." (PMID 37873776, 2023).
myeloid leukemia (4 papers, 2010 to 2023). A clonal proliferation of myeloid cells and their precursors in the bone marrow, peripheral blood, and spleen. "On the contrary, CRP inhibits proliferation, while induces apoptosis of human myeloid leukemia cell, which is in line with our observation in the HL-1 cells." (PMID 31391207, 2019). "We find that CRP inhibits proliferation of the human myeloid leukemia cell line Mono Mac 6 with an IC50 of 75 μg/ ml by inducing apoptosis of these cells." (PMID 29202702, 2017).
pancreatic neuroendocrine neoplasm (4 papers, 2017 to 2021). A neoplasm with neuroendocrine differentiation that arises from the pancreas. "In this study, we aimed to confirm pre-operative serum CRP as a prognostic factor for outcome and survival after surgical resection of pancreatic NEN independent from grading and tumour advancement." (PMID 34887479, 2021). "The tumour-derived cytokine IL-6, which is associated with high circulating levels of CRP, have been shown to be prognostic in pancreatic NENs, lending support to a CRP-based inflammatory score in NENs." (PMID 34439386, 2021). "Very recently, one study performed on 149 pancreatic neuroendocrine neoplasms demonstrated that CRP level is a new prognostic factor for survival." (PMID 28074897, 2017). "Pancreatic NEN with a T1 or T2 status and T3 or T4 tumours had a highly significant difference in survival stratified by serum CRP (p = 0.001 and p < 0.001, respectively)." (PMID 34887479, 2021). "We propose that serum CRP might be a factor worth evaluating for additional prognostic information of the ENETS or WHO guidelines and staging systems for pancreatic NEN." (PMID 34887479, 2021).
peripheral arterial occlusive disease (4 papers, 2007 to 2022). "Age was positively associated with BMI (p = 0.003), presence of peripheral arterial occlusive disease (p = 0.041), CRP levels (p = 0.001), and negatively associated with creatinine clearance (p < 0.0001)." (PMID 17295929, 2007). "Furthermore, patients with higher age, with left ventricular ejection fraction < 50, history of peripheral arterial occlusive disease and higher levels of c-reactive protein had a significantly higher hazard of death compared with those without these conditions." (PMID 34915852, 2021).
polyarteritis nodosa (4 papers, 2011 to 2025). Polyarteritis nodosa (PAN) is a rare, clinically heterogeneous, rheumatologic disease characterized by necrotizing inflammatory lesions affecting small- and medium-sized blood vessels. "The manifestations of polyarteritis nodosa in our patient were muscle pain and weakness, abdominal pain and elevated inflammatory markers including ESR, CRP, ferritin and platelets." (PMID 21718511, 2011).
Polypoidal choroidal vasculopathy (4 papers, 2010 to 2018). The presence of aneurysmal 'polypoidal' lesions in the choroidal vasculature. "Distribution of polypoidal choroidal vasculopathy cases and controls within tertiles of homocysteine and C-reactive protein levels." (PMID 25337797, 2014). "Plasma homocysteine and serum C-reactive protein levels in overall and different genders of patients with polypoidal choroidal vasculopathy and the control subjects." (PMID 25337797, 2014).
postpartum depression (4 papers, 2024 to 2025). A type of clinical depression that occurs after childbirth. "Both lower zinc and higher CRP were associated with prenatal and postnatal depression." (PMID 41228551, 2025). "As an example, while elevated inflammatory marker (CRP) was associated with increased depressive symptoms, it remains unclear whether inflammation contributes to the onset of postpartum depression or whether depressive symptoms themselves induce an inflammatory response." (PMID 40566031, 2025). "Another study’s outcomes show that elevated serum levels of high-sensitivity C-reactive protein (Hs-CRP) and interleukin-6 (IL-6) following delivery are positively associated with EPDS scores ≥12, a threshold indicative of increased risk for postpartum depression." (PMID 40566031, 2025). "These markers may interact with high-sensitivity CRP and IL-6, potentially influencing both the onset and severity of postpartum depression (PPD)." (PMID 40566031, 2025). "A systematic review highlighted that elevated CRP levels at the end of pregnancy or immediately after delivery could predict postpartum depression (PPD)." (PMID 40566031, 2025). "Their most robust finding was that levels of CRP in late pregnancy could predict postpartum depression." (PMID 38820411, 2024). "The immune shift following delivery may trigger a temporary increase in inflammation in susceptible individuals, with elevated levels of inflammatory markers, such as C-reactive protein (CRP), potentially indicating a connection between the immune response and postpartum depression." (PMID 40566031, 2025).
pouchitis (4 papers, 2013 to 2023). Acute inflammation in the intestinal mucosa of the continent ileal reservoir (or pouch) in patients who have undergone ileostomy and restorative proctocolectomy (proctocolectomy, restorative). "However, the accuracy of CRP to identify pouchitis was lower than that of fecal calprotectin, with an AUC of 0.59 compared to an AUC of 0.68 and no sensitivity or specificity was reported." (PMID 36778511, 2022). "The primary outcome was clinical improvement in pouchitis at 4 weeks after FMT assessed by patient surveys; secondary outcomes included decreases in composite PDAI at least 3 at week 4, erythrocyte sedimentation rate (ESR), C-reactive protein (CRP), and fecal calprotectin compared to baseline." (PMID 36777294, 2020). "Additionally, subclinical inflammation may be present in individuals with pre-colectomy UC, without a clinical diagnosis of pouchitis, as our finding of elevated levels of CRP among this group may suggest." (PMID 24086242, 2013). "Of note, the authors also measured C-reactive protein (CRP), which remained at a normal level and did not change significantly throughout the study duration in both patients with and without pouchitis." (PMID 36778511, 2022).
pregnancy-induced hypertension (4 papers, 2015 to 2024). "Furthermore, elevated levels of CRP may be more difficult to interpret, because factors such as premature rupture of membranes (PROM), maternal fever, pregnancy-induced hypertension, prenatal steroid use, fetal distress, and gestational age may influence its kinetics." (PMID 26380313, 2015).
pyogenic liver abscess (4 papers, 2019 to 2025). Single or multiple areas of PUS due to bacterial infection within the hepatic parenchyma. "An elevated CRP level, although indicative of systemic inflammation, shows limited specificity in differentiating infectious etiologies or disease progression stages in patients with pyogenic liver abscess." (PMID 41048965, 2025). "The purpose of the current study was to evaluate the association between C-reactive protein-to-platelet ratio (CPR), neutrophil-to-lymphocyte*platelet ratio (NLPR) and fibrinogen-to-platelet ratio (FPR) and the prognoses of pyogenic liver abscess (PLA) patients." (PMID 35864446, 2022). "A CRP ratio (defined as the CRP value obtained at that particular week compared to the CRP value at week 1 of diagnosis) of ≤0.278 at week 3 was shown to be a good marker (sensitivity 0.786; specificity 0.714) for predicting antibiotic therapy of <5 weeks in pyogenic liver abscess." (PMID 37109763, 2023).
pyomyositis (4 papers, 2012 to 2024). Pyomyositis (PM) is a rare primary bacterial infection of the skeletal muscle, usually resulting from hematogenous spread or due to muscle injury, and characterized by pain and tenderness in the affected muscle, fever and abscess formation. "Onthe other hand, elevations of both CRP and ESR are a goodindication of pyomyositis." (PMID 25347752, 2014).
Raynaud syndrome (4 papers, 2016 to 2024). "A laboratory work-up performed on April 5, 2012, in the context of the Raynaud's disease follow-up showed that immunologic tests and C-reactive protein (CRP) were negative and serum creatinine concentration was 91 μmol/L." (PMID 26955492, 2016).
rectal tumor (4 papers, 2009 to 2022). "Moreover, our results reveal that the CRP-286 SNP mutations tend to co-occur with mutant APC in colon and rectal tumors." (PMID 25025473, 2014). "In this study, we investigated immunohistochemically whether CRP is expressed in rectal tumour cells and evaluated its significance and malignant potential in colorectal carcinogenesis." (PMID 27956962, 2009). "The rationale to perform this investigation is that an immunohistochemical examination would demonstrate whether rectal tumours do express CRP and if so, it would represent the local inflammatory reaction to tumoral invasion." (PMID 27956962, 2009).
restless leg syndrome (4 papers, 2014 to 2024). "Another study found that severe periodic leg movements were linked with increased CRP in restless leg syndrome." (PMID 24663098, 2014). "Other data show higher CRP as a potential risk factor for Restless Legs Syndrome (RLS), associate the possibility of elevated CRP with severe periodic sleep leg movements in RLS cases, and highlight that moderately elevated hsCRP may be linked to systemic inflammation in RLS." (PMID 37873776, 2023).
Salmonella Infections (4 papers, 2016 to 2023). Infections with bacteria of the genus SALMONELLA. "Both ZS2058 (161.4 μg/L) and LGG treatments (161.8 μg/L) were associated with reduced levels of CRP, indicating an alleviation of Salmonella infection in vivo." (PMID 30842764, 2019).
scleritis (4 papers, 2022 to 2025). Inflammation of the sclera. "She developed scleritis and relapsed twice, with elevation of serum disease markers such as ANCA titer and C-reactive protein." (PMID 37662600, 2023).
selenium deficiency (4 papers, 2014 to 2024). A nutritional deficiency disease resulting from inadequate selenium levels in the body, which can lead to impaired function of selenoproteins essential for antioxidant defense and thyroid hormone metabolism. "Selenium deficiency is generally associated with elevated serum levels of C-reactive protein (CRP), a biomarker of inflammation." (PMID 38068774, 2023). "Further adjusting for inflammation (CRP) (Multivariable model 2) did not change the lack of association (aHR: 1.14, 95% CI: 0.49–2.61) between serum selenium deficiency and clinical failure." (PMID 25401501, 2014). "However, as selenium and inflammation have a bi-directional relationship, it is possible that CRP might not be a risk factor but a result of selenium deficiency as deficiency can also lead to changes in inflammation." (PMID 25401501, 2014).
silicosis (4 papers, 2021 to 2025). Silicosis is a respiratory disease caused by breathing in (inhaling) silica dust. "We have checked on the relation between the complicated silicosis and the CRP, ESR fibrinogen, and LDH levels and found significant association with the progression of silicosis, even though in CS group both CRP and ESR were correlated with KL-6 serum levels." (PMID 40547914, 2025). "IL-8, LDH, andAAT levels were associated with progression of silicosis, and IL-6, IL-8, LDH, AAT,ferritin, and CRP levels were associated with a fatal outcome." (PMID 39606764, 2024). "IL-8, LDH and AAT levels were associated with progression of silicosis and IL-6, IL-8, LDH, AAT, ferritin, and CRP with vital status." (PMID 34172787, 2021). "To improve the robustness of the biomarker set, we crossed the biomarkers screened by the three machine learning algorithms, LASSO, SVM, and RF, and finally developed a biomarker set that included eight potential diagnostic biomarkers for silicosis (A/G, ALB, CRP, DD, GLU, LDH, RBC, and WBC)." (PMID 39882130, 2024). "Among selected biomarkers, WBC, RBC, ALB, GLU, and A/G showed lower levels in the silicosis group, while LDH, DD and CRP had the opposite trend." (PMID 39882130, 2024). "Patientsdiagnosed with complicated silicosis had higher levels of IL-2R, IL-6, IL-8, AAT,ferritin, CRP, and LDH than those diagnosed with simple silicosis." (PMID 39606764, 2024). "Clinical biochemistry in the silicosis group confirmed significant increases in inflammatory markers including AST, CKMB, CRP, HBDH, and LDH." (PMID 39882130, 2024). "LDH, alpha 1- antitrypsin, ferritin and CRP showed significant differences between complicated silicosis and exposed and simple silicosis but not between exposed and simple silicosis, and IL-6 showed differences only between complicated and simple silicosis." (PMID 34172787, 2021). "Likewise, patients diagnosed with silicosis showed higher levels of IL-8, AAT, CRP and LDH than exposed patients, and patients diagnosed with complicated silicosis showed higher levels of IL2R, IL-6 IL-8, AAT, ferritin, CRP and LDH than those diagnosed with simple silicosis." (PMID 34172787, 2021). "IL-8, α1AT, ferritin, CRP and LDH levels were higher in silicosis than in those exposed to silica without silicosis." (PMID 34172787, 2021).
skin cancer (4 papers, 2018 to 2025). "Both had clinically severe disease and belonged to complementation group E. These two participants had high levels of CRP, seemingly correlating with the severe skin cancers they had developed in their lifetime." (PMID 35223501, 2022). "However, the remaining participants (n=9) with low CRP levels had severe clinical disease, having been operated on several times for excision of skin cancers and other skin tumors." (PMID 35223501, 2022).
spinal stenosis (4 papers, 2011 to 2023). Narrowing of the spinal canal. "Nevertheless, there are studies that showed that CRP is associated with postoperative outcomes in disc herniation and spinal stenosis." (PMID 37803313, 2023). "Two patients were still on low dose steroids due to residual lower limb pain despite complete remission of the rash and consistently normal CRP levels (1 had hip osteoarthritis, 1 spinal stenosis)." (PMID 33208192, 2020).
splenic abscess (4 papers, 2014 to 2025). An abscess that is located in the spleen. "Our study found that the combination of immunomodulatory treatments reduced relapse in females and individuals with splenic abscess or CRP > 12 mg/dL." (PMID 40843703, 2025). "On investigations the CRP was 227 and abdominal computed tomography (CT) revealed a splenic abscess." (PMID 32276217, 2020). "However, the approach of prescribing CS in combination with another immunomodulatory treatment as a first-line choice was found to be beneficial toward relapse only for females and patients who had CRP > 12 mg/dL or splenic abscesses." (PMID 40843703, 2025). "Diagnosis of splenic abscesses caused by C. difficile remains challenging due to non-specific symptoms (fever, weight loss, abdominal pain) and laboratory findings (elevated white blood cell count, elevated or normal CRP value)." (PMID 40723972, 2025).